BRIP1 (BRCA1 interacting DNA helicase 1)
Description:
DNA-dependent ATPase and 5'-3' DNA helicase required for the maintenance of chromosomal stability. Acts late in the Fanconi anemia pathway, after FANCD2 ubiquitination. Involved in the repair of DNA double-strand breaks by homologous recombination in a manner that depends on its association with BRCA1. Involved in the repair of abasic sites at replication forks by promoting the degradation of DNA-protein cross-links: acts by catalyzing unfolding of HMCES DNA-protein cross-link via its helicase activity, exposing the underlying DNA and enabling cleavage of the DNA-protein adduct by the SPRTN metalloprotease. Can unwind RNA:DNA substrates. Unwinds G-quadruplex DNA; unwinding requires a 5'-single stranded tail.
Synonyms: BACH1; FANCJ; OF
Tractability: PROTAC: ubiquitination databases record sites on it; its protein half-life has been measured.
Gene: Protein-coding gene on chromosome 17 (61,679,139 to 61,863,561, reverse strand). Ensembl gene ENSG00000136492.
Subcellular location: Nucleus; Cytoplasm
Subcellular location (Human Protein Atlas): Nuclear membrane; Nucleoplasm
Pathways (Reactome):
DNA Repair: HDR through Homologous Recombination (HRR); HDR through Single Strand Annealing (SSA); Homologous DNA Pairing and Strand Exchange; Presynaptic phase of homologous DNA pairing and strand exchange; Processing of DNA double-strand break ends; Resolution of D-loop Structures through Holliday Junction Intermediates; Resolution of D-loop Structures through Synthesis-Dependent Strand Annealing (SDSA)
Disease: Defective HDR through Homologous Recombination Repair (HRR) due to PALB2 loss of BRCA1 binding function; Defective HDR through Homologous Recombination Repair (HRR) due to PALB2 loss of BRCA2/RAD51/RAD51C binding function; Defective homologous recombination repair (HRR) due to BRCA1 loss of function; Impaired BRCA2 binding to PALB2; Impaired BRCA2 binding to RAD51
Cell Cycle: G2/M DNA damage checkpoint
Metabolism: Cytosolic iron-sulfur cluster assembly
Gene Ontology:
Molecular function: 5'-3' DNA helicase activity; ATP hydrolysis activity; G-quadruplex unwinding activity; protein binding; DNA binding; DNA helicase activity; ATP binding; helicase activity; hydrolase activity, acting on acid anhydrides, in phosphorus-containing anhydrides; nucleic acid binding
Biological process: protein-DNA covalent cross-linking repair; regulation of transcription by RNA polymerase II; DNA damage checkpoint signaling; DNA repair; double-strand break repair; double-strand break repair involved in meiotic recombination; homologous recombination; nucleotide-excision repair
Cellular component: BRCA1-B complex; cytoplasm; nuclear membrane; nucleoplasm; nucleus; replication fork
Genetic constraint (gnomAD): Loss-of-function variants: 79 observed, 112.29 expected, observed/expected ratio (o/e) 0.7, 90% interval 0.59 to 0.85. The upper end of that interval is the gene's LOEUF score, 0.85, which puts it in group 3 of 6, group 1 being the genes least tolerant of losing a copy. Missense variants: 1,230 observed, 1,490.8 expected, observed/expected ratio (o/e) 0.83, 90% interval 0.79 to 0.87. Synonymous variants: 435 observed, 512.68 expected, observed/expected ratio (o/e) 0.85, 90% interval 0.78 to 0.92.
Gene-disease validity (ClinGen):
ClinGen rates the evidence that BRIP1 causes each of these diseases.
familial ovarian cancer (autosomal dominant): Definitive. An instance of ovarian cancer that is caused by an inherited modification of the individual's genome.
Fanconi anemia complementation group J (autosomal recessive): Definitive. Fanconi anemia caused by mutations in the BRIP1 gene, encoding Fanconi anemia group J protein.
hereditary breast carcinoma (autosomal dominant): Refuted. Breast carcinoma that has developed in relatives of patients with history of breast carcinoma.
Cancer hallmarks: genome instability and mutations (suppresses)
Homologues: Orthologues: chimpanzee BRIP1 (99% identical), macaque BRIP1 (91% identical), dog BRIP1 (83% identical), rabbit BRIP1 (80% identical), pig BRIP1 (78% identical), mouse Brip1 (70% identical), guinea pig BRIP1 (66% identical), tropical clawed frog brip1 (51% identical), zebrafish brip1 (47% identical), Caenorhabditis elegans dog-1 (21% identical). Paralogues in human: RTEL1 (22% identical), DDX11 (17% identical), ERCC2 (14% identical).
Diseases named in the same sentence as BRIP1 in open-access papers:
BRIP1 is named in the same sentence as 161 diseases in open-access papers, as found by Europe PMC text mining. Sharing a sentence is not in itself a finding about the gene and the disease. The quoted sentences say what the papers report.
breast cancer (217 papers, 2005 to 2026). A primary or metastatic malignant neoplasm involving the breast. "One NOA patient with bilateral cryptorchidism and severe hypospadias carried two previously reported truncating variants in FA genes, BRIP1 p.Thr912fs and RAD51C c.1026 + 5_1026 + 7del." (PMID 40060932, 2025). "Beyond breast cancer, BRIP1 mutations have been implicated in multiple other malignancies, including cervical, ovarian, and prostate cancers." (PMID 41597333, 2025). "Studies in BRIP1-mutated breast cancer, ovarian cancer, and prostate cancer suggest a clinical benefit of PARP-inhibitor use." (PMID 40988318, 2025). "BRIP1 is a DNA helicase involved in homologous recombination and has been associated with ovarian cancer, breast cancer and Fanconi’s anemia." (PMID 39192095, 2024). "In contrast to normotensive patients, PE plasma presented an increase in BRIP1 expression, which is linked to genetic instability and commonly observed in women with cervical or breast cancer and postmenopausal CVD." (PMID 39587642, 2024). "BRIP1 gene was closely related to the function of breast cancer susceptibility BRCA1 (breast cancer 1, early onset), also known as BACH1 or FANCJ, located on 17q22-q24, about 18Kb, composed of 20 exons and 19 introns." (PMID 39211736, 2024). "Previous studies regarded BRIP1 as a tumor suppressor gene and revealed its diagnostic role in various types of cancer, such as breast cancer, ovarian cancer, cervical cancer, and colon cancer." (PMID 37153833, 2023). "A cohort of more than 117000 patients elucidated the missense variant of BRIP1 conferred risk for ovarian and breast cancer." (PMID 37153833, 2023). "The National Comprehensive Cancer Network (NCCN) guidelines identified BRIP1 as a potential risk factor for breast cancer, especially for triple negative breast cancers." (PMID 37153833, 2023). "Other studies have also identified BRIP1 mutations (c.2392C>T) in an Irish cohort comprising patients with breast cancer diagnosed at <42 years of age and the p.Q994E mutation in Chinese patients with early-onset breast cancer diagnosed at <35 years of age." (PMID 36980802, 2023). "BRIP1 mutation was found in the proband's mother, indicating that it was related to the cancer cases observed on the maternal side, including breast cancer and sarcoma." (PMID 36833355, 2023). "The BC susceptibility genes involved in breast cancer which cause moderate risk are BRIP1, CHEK2, ATM, RAD51C, and PALB2." (PMID 36873936, 2023). "Single PVs were identified in other genes associated with breast cancer risk, BRIP1 (c.2392C>T; p.Arg798Ter), RECQL (c.1667_1667+3delAGTA; p.)?" (PMID 33758026, 2022). "Several truncating variants of BRIP1 are conventionally known to be associated with breast cancer with low or moderate penetrance." (PMID 35008774, 2021). "Mutations in BRIP1 increases the risk of breast and ovarian cancer, and its impairment accounts for some breast cancer familial cases." (PMID 33662042, 2021). "In the study by Tung and collaborators, among 488 patients with breast cancer, four women (0.81%) had a pathogenic variant in the BRIP1 gene." (PMID 33134171, 2020). "This work is consistent with a previous study that truncating mutations in BRIP1/FANCJ confer susceptibility to breast cancer." (PMID 32120966, 2020). "Further studies illustrated that BRIP1 was a low/moderate-penetrance breast cancer susceptibility gene." (PMID 32300589, 2020). "Previous researches reported that the inherited mutation in the BRIP1 gene is associated with the increased risk of breast cancer." (PMID 30975222, 2019).
breast cancer (continued). "The BRIP1 gene was originally suggested to be a low‐penetrant breast cancer susceptibility gene, but, later studies suggested that the risk was elevated for ovarian cancer." (PMID 30689231, 2019). "Pathogenic germline mutations in BRIP1 are known to confer about 10% cumulative risk of ovarian cancer and also associated with an increased risk of female breast cancer." (PMID 31064327, 2019). "Eventually, the mother, who transmitted the BRIP1 variant, was diagnosed with breast cancer at the age of 46." (PMID 29507082, 2018). "Germline mutations in the BRIP1 gene have been described as conferring a moderate risk for ovarian cancer (OC), while the role of BRIP1 in breast cancer (BC) pathogenesis remains controversial." (PMID 29368626, 2018). "Women who inherit one mutated copy of BRIP1 are likely to have an increased risk of ovarian cancer; however, the implication of this for breast cancer risk is inconclusive." (PMID 30353044, 2018). "As heterozygous carriers of truncating mutations in BRIP1 have been reported to be susceptible to breast cancer, this VUS entry represents a pathogenic low penetrance classification that is currently not amenable to ClinVar submission requirements." (PMID 29308099, 2018). "In two patients with early-onset breast cancer, mutations in the BRIP1 coding regions resulted in a defective helicase activity." (PMID 28968953, 2017). "Since it is critical for the BRCA-associated DNA damage repair process the BRIP1 gene has been associated with other types of cancer, especially breast cancer." (PMID 27415837, 2016). "We identified and validated several known metastasis mediators as regulated by MMP9, including Foxq1 and PLAU, as well as the suspected breast cancer susceptibility gene BRIP1." (PMID 24811362, 2014). "So far, mutations of the BRIP1 gene have been associated with FA in the biallelic state and with breast cancer in the monoallelic state, although the risk for breast cancer appears moderate." (PMID 24025454, 2013). "Several loss-of-function mutations in BRIP1 gene have been reported in breast cancers and also in the cancer-prone disease Fanconi anemia." (PMID 24040146, 2013). "BRIP1 (also known as BACH1 and FANCJ) is a DNA helicase that interacts directly with the breast cancer susceptibility protein BRCA1." (PMID 24040146, 2013). "Most currently known breast cancer predisposition genes play a role in the repair of DNA double-strand breaks by homologous recombination: BRCA1 and BRCA2, associated with a high risk of breast cancer, and BRIP1 and PALB2, associated with a moderate risk." (PMID 24139550, 2013). "BRIP1 is one of these genes and truncating mutations confer a 2-fold increase in breast cancer risk." (PMID 24040146, 2013). "Truncating mutations in the BRIP1/FANCJ gene have recently been shown to be associated with a moderate risk of breast cancer." (PMID 19127258, 2009). "We used a SNP tagging approach to evaluate the association between common variants (minor allele frequency≥0.05) in BRIP1 and the risks of breast cancer and invasive ovarian cancer." (PMID 17342202, 2007). "It is unlikely that common variants in BRIP1 contribute significantly to breast cancer susceptibility." (PMID 17342202, 2007). "Previous studies have looked at the association between a handful of common functional BRIP1 polymorphisms and breast cancer risk." (PMID 17342202, 2007). "Very recently, a rare ptotein truncating variant in BRIP1 has been identified as low-penetrance breast cancer susceptibility alleles." (PMID 17342202, 2007). "While consensus was not reached for recontact of individuals with a GPV in intermediate penetrance CSGs (RAD51C and RAD51D) with respect to breast cancer risk management, consensus was reached for recontact for these genes (and BRIP1) with respect to ovarian cancer risk management." (PMID 41159931, 2025).
breast cancer (continued). "Alterations in BRIP1 that impair its helicase function have been identified in patients with early-stage breast cancer, and several of these missense variants are considered to confer increased susceptibility to breast cancer." (PMID 41597333, 2025). "Accordingly, BRIP1 is classified as a moderate-penetrance breast cancer susceptibility gene." (PMID 41597333, 2025). "BRCA2 gene mutations are associated with an increased risk of male breast cancer, along with lesser-known gene mutations that could also increase this risk, such as mutations of the BRIP1 gene." (PMID 38912178, 2024). "Additionally, heterozygous mutation of Brip1 predisposes to early onset breast cancer supporting its role in hereditary breast cancer development and BRCA1-related DNA repair mechanisms." (PMID 35105904, 2022). "Furthermore, a polymorphic variation within the BRIP1 is a risk factor for meningioma development and was also identified in breast cancer patients." (PMID 33674888, 2021). "Additionally, pathogenic alterations in PALB2, ATM, CHEK2, and NBN are correlated with an increased risk for breast cancer and/or other cancers, whereas other genes such as BRIP1, RAD51C, and RAD51D are associated with an increased ovarian cancer risk." (PMID 32733558, 2020). "However, the effect of germline BRIP1 mutations in the risk of breast cancer is still controversial." (PMID 30975222, 2019). "Indeed, the presence of the BRIP1 mutation is very challenging for genetic counsellors as they should take into consideration not only the FA risk for the descendants but also the breast cancer risk for the ascendants." (PMID 31124294, 2019). "However, previous studies declared that BRIP1 mutation not only has effect on breast cancer, but also in other various cancers including cervical cancer, ovarian cancer and prostate cancer." (PMID 29466248, 2018). "In addition, BRIP1 germline mutations have been identified in breast cancer patients, and in prostate cancer patients with at least one additional cancer." (PMID 29755699, 2018). "In addition, mutations in the CHEK2, ATM and BRIP1 genes confer a moderate lifetime risk of breast cancer but are rare and account for less than 5 % of familial breast cancer cases." (PMID 26553136, 2015). "In addition, Huo et al62 used PCR-primer introduced restriction analysis assays to genotype the rs4986764 polymorphism of BRIP1 in a case-control study of 568 breast cancer cases and 624 controls in a Chinese population." (PMID 23318652, 2013). "Recently, three BRIP1 missense mutations have been identified in high-risk Jewish women, who have been tested negative for mutations in BRCA1 and BRCA2 genes, indicating that BRIP1 mutations can contribute to breast cancer susceptibility in Jewish high-risk families." (PMID 23586058, 2013). "This may be related to the fact that BRIP1 is categorized as a moderate risk gene for breast cancer." (PMID 24040146, 2013). "Recent studies implicate BRIP1 as a moderate/low-penetrance breast cancer susceptibility gene." (PMID 24040146, 2013). "Therefore, it is unlikely that common variants in BRIP1 contribute significantly to breast cancer risk." (PMID 17342202, 2007). "Germline BRIP1 mutations are associated with breast cancer and Fanconi anemia." (PMID 17342202, 2007). "Overall, studies have estimated that there is a 1.2- to 3.2-fold higher risk for developing breast cancer in patients <40 years of age with identified BRIP1 mutations compared to non-carriers, and that 1% of patients with early-onset or familial breast cancer carried a deleterious BRIP1 mutation." (PMID 36980802, 2023). "Missense mutations in BRIP1 may increase breast cancer risk." (PMID 29466248, 2018).